H2BC10 (H2B clustered histone 10)
Description:
Core component of nucleosome. Nucleosomes wrap and compact DNA into chromatin, limiting DNA accessibility to the cellular machineries which require DNA as a template. Histones thereby play a central role in transcription regulation, DNA repair, DNA replication and chromosomal stability. DNA accessibility is regulated via a complex set of post-translational modifications of histones, also called histone code, and nucleosome remodeling. Has broad antibacterial activity. May contribute to the formation of the functional antimicrobial barrier of the colonic epithelium, and to the bactericidal activity of amniotic fluid.
Synonyms: H2B/k; H2BC4; H2BFK; HIST1H2BI; H2BC6; H2BC7; H2BC8
Gene: Protein-coding gene on chromosome 6 (26,272,931 to 26,273,412, forward strand). Ensembl gene ENSG00000278588.
Subcellular location: Nucleus; Chromosome
Subcellular location (Human Protein Atlas): Nucleoplasm; Cytosol
Pathways (Reactome):
Gene expression (Transcription): B-WICH complex positively regulates rRNA expression; DNA methylation; ERCC6 (CSB) and EHMT2 (G9a) positively regulate rRNA expression; MLL4 and MLL3 complexes regulate expression of PPARG target genes in adipogenesis and hepatic steatosis; NoRC negatively regulates rRNA expression; PRC2 methylates histones and DNA; RNA Polymerase I Promoter Escape; RNA Polymerase I Promoter Opening; RUNX1 regulates genes involved in megakaryocyte differentiation and platelet function; RUNX1 regulates transcription of genes involved in differentiation of HSCs; Regulation of endogenous retroelements by KRAB-ZFP proteins; Regulation of endogenous retroelements by Piwi-interacting RNAs (piRNAs); Regulation of endogenous retroelements by the Human Silencing Hub (HUSH) complex; SIRT1 negatively regulates rRNA expression; Transcriptional regulation by small RNAs
Chromatin organization: CHD1 and CHD2 subfamily; CHD6, CHD7, CHD8, CHD9 subfamily; ChAHP complex assembly; HATs acetylate histones; HDACs deacetylate histones; Interaction of NuRD complexes with transcription factors; NuRD complex assembly
DNA Repair: Cleavage of the damaged purine; Cleavage of the damaged pyrimidine; Nonhomologous End-Joining (NHEJ); Processing of DNA double-strand break ends; Recognition and association of DNA glycosylase with site containing an affected purine; Recognition and association of DNA glycosylase with site containing an affected pyrimidine; Recruitment and ATM-mediated phosphorylation of repair and signaling proteins at DNA double strand breaks
Cell Cycle: Condensation of Prophase Chromosomes; Deposition of new CENPA-containing nucleosomes at the centromere; G2/M DNA damage checkpoint; Inhibition of DNA recombination at telomere; Packaging Of Telomere Ends
Developmental Biology: Activation of anterior HOX genes in hindbrain development during early embryogenesis; Chromatin modifications during the maternal to zygotic transition (MZT); Replacement of protamines by nucleosomes in the male pronucleus; Transcriptional regulation of granulopoiesis
Disease: Defective pyroptosis; Dengue Virus-Host Interactions
and 18 more pathways
Gene Ontology:
Molecular function: identical protein binding; protein binding; DNA binding; structural constituent of chromatin; protein heterodimerization activity
Biological process: antibacterial humoral response; antimicrobial humoral immune response mediated by antimicrobial peptide; defense response to Gram-positive bacterium; innate immune response in mucosa; chromatin organization; nucleosome assembly
Cellular component: extracellular exosome; extracellular region; nucleus; nucleoplasm; nucleosome; chromosome
Genetic constraint (gnomAD): Loss-of-function variants: 6 observed, 6.66 expected, observed/expected ratio (o/e) 0.9, 90% interval 0.49 to 1.68. That is too few expected variants to judge how well the gene tolerates losing a copy. Missense variants: 191 observed, 178.93 expected, observed/expected ratio (o/e) 1.07, 90% interval 0.95 to 1.2. Synonymous variants: 120 observed, 78.03 expected, observed/expected ratio (o/e) 1.54, 90% interval 1.33 to 1.79.
Homologues: Orthologues: chimpanzee H2BC4 (100% identical), macaque H2BC4 (100% identical). Paralogues in human: H2BC4 (100% identical), H2BC6 (100% identical), H2BC7 (100% identical), H2BC8 (100% identical), H2BC12 (99% identical), H2BC15 (99% identical), H2BC21 (99% identical), H2BC5 (99% identical), H2BC9 (99% identical), H2BC11 (98% identical), H2BC13 (98% identical), H2BC17 (98% identical), and 9 more.
Diseases named in the same sentence as H2BC10 in open-access papers:
H2BC10 is named in the same sentence as 1 disease in open-access papers, as found by Europe PMC text mining. Sharing a sentence is not in itself a finding about the gene and the disease. The quoted sentences say what the papers report.
tumor (1 paper, 2025). "CDH5, ID1, H2BC10, and ITLN1 were common DEGs in the tumor and stroma areas." (PMID 40422184, 2025).